HMGA2 (high mobility group AT-hook 2)
Diseases named in the same sentence as HMGA2 in open-access papers (continued):
Sharing a sentence is not in itself a finding about the gene and the disease.
tumor (continued). "Necrosis and hemorrhage positivity were rare and no statistical differences could be derived: four tumors were positive for necrosis (2 NR MED12; 1 GR non-MH; 1 VGR HMGA2) and one tumor was positive for hemorrhage (VGR non-MH)." (PMID 36048862, 2023). "KP tumor organoid cells could be separated into two cell states resembling the states defined in GEMM, one resembling AT2 cells and one similar to the EMT-like state (Hmga2-high)." (PMID 36993454, 2023). "KY tumor organoids did not exhibit evidence of the Hmga2-high Group 4 cell state." (PMID 36993454, 2023). "HMGA2 can effectively adjust EMT through the PI3K/AKT, MAPK/ERK, TGFB/Smad, NFrB, and STAT3 signaling pathways, enabling HCC cells to invade local tissues, get the penetrating ability of intravascular, and give birth to offspring with the tumor-initiating ability." (PMID 37689710, 2023). "Therefore, the claim that HMGA2 promotes tumor drug resistance is not absolute, and more clinical trials are needed to confirm it." (PMID 38304037, 2023). "In addition, the tumor tissues of oe-circ_0000658-treated mice exhibited reduced β-catenin and E-cadherin, as well as elevated N-cadherin, Slug, Snail, ZEB1 and Twist, whereas further inhibition of HMGA2 reversed this effect relative to oe-circ_0000658 alone." (PMID 35031054, 2022). "To our knowledge, we have, for the first time, reported that HMGA2 bound directly to the -743/-730 and -585/-576 promoter regions of STAT3 and in turn promoted its transcription and expression, thus enhancing tumor immune evasion and facilitating tumor progression in CRC." (PMID 34976223, 2022). "Nevertheless, HMGA2 could be detected in some non-malignant pancreatic ducts but its expression was higher in tumor tissue compared to non-malignant tissue, especially in the nuclei." (PMID 34302528, 2021). "HMGA2 showed negative correlations (r = −0.30~−0.48, p < 0.05) with tumor infiltration by Th17 cells, monocytes, and macrophages and positive correlations (r = 0.33~−0.57, p < 0.05) with tumor infiltration of B cells, NKT cells, nTregs, and CD8-naive cells." (PMID 34831096, 2021). "Moreover, cytoplasmic staining of HMGA2 was present with similarly low intensity in tumor and normal tissue (negative to weak positive in 28/28 and 26/28 cases, respectively; p = 0.5)." (PMID 34302528, 2021). "Therefore, HMGA2 regulated RD-HIST expression and drove tumor progression." (PMID 34206586, 2021). "As a tumor suppressor or tumor promoter, miR-let-7b has been found to halt cell proliferation, adhesion, and invasion by targeting Protein Code Gene (PKA1), Diaphanous Related Formin 2 (DIAPH2), Radixin (RDX), RAS, MYC, and High Mobility Group A2 (HMGA2) genes and their respective proteins." (PMID 34122072, 2021). "Raised HMGA2 levels that occur with alterations in the TGF-β signaling pathway may reflect an altered activity of E3 ligases, such as PJA1, and potentially contribute to the tumor-promoting roles of TGF-β signaling." (PMID 32577156, 2020). "The remaining 3 tumours showed absent or weak expression of HMGA2 mRNA in T0 and during culture." (PMID 32251338, 2020). "Although most regulatory elements in the HMGA2 3’ UTR have been found to induce HMGA2 expression such as AU-rich elements (AREs) that interact with HuR ARE-binding protein, repressive regulatory elements include characteristic binding sites for the tumor suppressor microRNA let-7 family." (PMID 32365712, 2020). "Finally, treatment with rapamycin induced LC3-II, ATG7, ATG12 and Bcl2 expression and reduced the levels of SQSTM1/p62 and Bax, indicating that autophagy can protect tumour cells from the negative effects of HMGA2 knockdown." (PMID 31053152, 2019). "The presence of HMGA2 enhanced DNA damage‐induced PARP1 activation, suggesting that higher concentrations of PARP1 inhibitor olaparib may be required to block PARP1 activity in HMGA2 expressing tumor cells." (PMID 30289618, 2019).
tumor (continued). "Interestingly, although HMGA2 protein was not detectable by IHC in any tumor sample, we observed HMGA2 mRNA levels in most of the cell lines and apparently high levels of this protein in several of them." (PMID 31188873, 2019). "Furthermore, histological analysis of the tumours from gemcitabine treated KPKOC;Hmga2+/+ and KPKOC;Hmga2CK/CK mice uncovered comparable histology, with complete destruction of normal pancreatic architecture and development of undifferentiated and anaplastic PDAC." (PMID 30228296, 2018). "Although several studies have reported that NANOG and HMGA2 could regulate Snail2 to affect tumor invasion and metastasis, few studies have investigated the relationship between Snail2 and EMT in CRC, and its implications in tumor progression." (PMID 30541610, 2018). "Furthermore, several studies have shown the importance of HMGA2 expression for metastasis and tumor progression in different malignancies but not yet in iCCA48–53." (PMID 30006612, 2018). "Moreover, HMGA2 increases SLUG expression, promoting or contributing to tumor progression." (PMID 29383160, 2017). "Only 3 out of 7 cases in which we could not detect HMGA2 mRNA in the plasma were positive for HMGA2 expression at the tumor level." (PMID 25749380, 2015). "Although the regulation of HMGA2 by let-7 miRNAs is not unique to AT/RT and has been previously discussed in breast, lung, and ovarian cancers, it provides a new therapeutic avenue in management of AT/RT tumours." (PMID 26064134, 2015). "Thus, the overexpression of HMGA1 and HMGA2 may be involved in the carcinogenesis and progression of RMS, and these two genes may also be prognostic indicators of the tumor and provide a new basis for targeted therapy." (PMID 24743780, 2014). "Thus, in our study we investigated the expression levels of HMGA1, HMGA2, Lin28, let-7 a and mir-98 via relative real time PCR in human and canine non-neoplastic and tumour tissue samples and human and canine cell lines which derived from primary OSCCs." (PMID 25245141, 2014). "Thus by virtue of its selective overexpression in tumor cells and likely role in CSC maintenance, HMGA2 may constitute a therapeutic target of interest." (PMID 21853155, 2011). "Interestingly, most of these tumours related to the alteration in HMGA2 are of nonepithelial origin." (PMID 14647145, 2003). "Although there are currently no targeted drugs for HMGA2, in previous clinical trials, we found that inhibiting the expression of HMGA2 with antisense oligonucleotide-modifying enzymes can effectively inhibit the proliferation and malignant transformation of tumor cells." (PMID 38304037, 2023). "Our results indicated that the overexpression of RhoC was closely related to tumor metastasis of OSCC, while knockdown of RhoC restrained the invasion and metastasis capability of OSCC cells in vivo and in vitro, and these effects may be related to the regulation of HMGA2 expression." (PMID 33519932, 2021). "Finally, the expressions of miR-23b and miR-130b, which target HMGA2 and CCNA2 genes, have been reported as down-regulated in somatotroph, gonadotroph, and silent PitNETs, while miR-183, which targets KIAA0101, appears to be down-regulated in aggressive lactotroph tumours." (PMID 32316225, 2020). "However, although our results show HMGA2 upregulation in EEC samples, they may not account for tumor invasion as we did not observe any correlation between HMGA2 expression levels and those of the EMT regulators—SNAIL, SLUG and TWIST (data not shown)." (PMID 31096664, 2019). "The percentage of HMGA2-positive tumors was similar in both groups, again supporting the idea that inactivation of CIC had no impact on tumor progression (Fig. EV1G,H)." (PMID 41219537, 2025). "All five tumors harbored an HMGA2 rearrangement as well, suggesting that DEPDC5 is involved in tumor progression rather than initiation." (PMID 35822448, 2023).
tumor (continued). "Moreover, the level of HMGA2 in circulating exosomes is significantly higher in NPC patients with metastasis than in those without metastasis and healthy negative controls, and the level of HMGA2 in tumor cells is associated with TJ and EndMT protein expression in endothelial cells." (PMID 35388172, 2022). "Knockdown of HMGA2 in the luminal cell line MCF-7 also affected cell proliferation, suggesting that the tumor-promoting functions of HMGA2 are not restricted to TNBC." (PMID 34680349, 2021). "Despite these promising results potentially implicating HMGA2 in tumor formation, we were not able to confirm this using a TNBC xenograft model with HMGA2 knockdown." (PMID 34680349, 2021). "However, we did not observe evidence for accelerated tumor progression or a shift towards more aggressive lesions in the absence of functional CIC, as demonstrated by HMGA2 immunostaining as a marker for lung tumor progression and invasion (Fig. EV1C–E)." (PMID 41219537, 2025). "Collectively, our results demonstrate that the non-metabolic activity of 6PGD regulates ALKBH5 and promotes global m6A modification in CRC, adding another dimension to the regulation of CRC tumor growth and metastasis through the MDM2-CCNA2/HMGA2 axis in a non-metabolic manner." (PMID 40611205, 2025). "However, Hmga2 showed no underexpression in any cancer type in either the GEPIA or Oncopression datasets and was upregulated in 16 out of 19 tumour types." (PMID 40182023, 2025). "Moreover, there was a positive correlation between the expression levels of HMGA2 and hsa_circ_0005325 and a negative correlation between the expression levels of HMGA2 and miR‐433‐3p in OSCC tumor tissues." (PMID 40900300, 2025). "Our future studies will focus on circulating tumor-derived exosomal HMGA2 as a plasma-based biomarker for noninvasive screening of patients for NPC metastases, along with testing targeted therapies aimed at blocking HMGA2 to halt metastasis." (PMID 35388172, 2022). "Immunohistochemistry for Hmga2, tdTomato, and the GFP fusion protein confirmed that Hmga2 expression in neoplastic cells in KP172CT;Hmga2CK/+ mice overlaps with GFP expression and that Hmga2 protein is absent from all tumours in KP172CT;Hmga2CK/CK mice." (PMID 30228296, 2018). "Moreover the tumours of the mice lacking E2F1 were smaller and slower growing than those developed by the HMGA2 mice." (PMID 16914062, 2006). "Additionally, we have not determined whether both cell states are required for tumor progression through paracrine signaling; the SPC-high state may rely on the HMGA2-high state or vice versa." (PMID 39930268, 2025).
cancer (397 papers, 2003 to 2026). A tumor composed of atypical neoplastic, often pleomorphic cells that invade other tissues. "HMGA2-mediated transcriptional regulation is clinically associated with dysregulated cancer progression, accelerated metastasis, and adverse overall survival in multiple malignancies, including CRC." (PMID 41249628, 2025). "Both studies indicated that that the expression of HMGA2 was increased in BC tissues compared with adjacent normal tissues, and the higher levels of HMGA2 protein expression were associated with advanced cancer grade and stage." (PMID 40204943, 2025). "Many studies have indicated that the High Mobility Group A2 (HMGA2) protein is a potential diagnostic and prognostic cancer marker due to its multifaceted role in cancer development and progression." (PMID 40204943, 2025). "In contrast, our AI-based pipeline introduces a robust method to identify and quantify HMGA2, a biomarker associated with cancer metastasis and resistance therapy, as examined through RISH." (PMID 41516076, 2025). "Numerous studies have demonstrated that elevated levels of HMGA2 are associated with poor prognosis in various cancers." (PMID 40853523, 2025). "Tumoral expression of chromatin remodeler protein HMGA2 is extensively linked to cancer metastasis and therapeutic resistance." (PMID 39858465, 2025). "Prior studies also identified HMGA2 germline variants linked to cancer predisposition and acquired genomic lesions in HMGA1 or HMGA2 linked to myeloid malignancy." (PMID 40076747, 2025). "While the overall risk of malignancy is relatively low, a distinct molecular sub-group harboring HMGA2 alterations seems to show an increased risk of malignant progression to carcinoma ex pleomorphic adenoma." (PMID 40338436, 2025). "An association of MDM2 amplification in 4 HMGA2-overexpressing carcinomas ex PA with particular gear-like nuclear atypia was recently reported, prompting further analysis of the phenomenon in our study." (PMID 40033554, 2025). "Intriguingly, this suggests that cancer initiation can occur solely through epigenetic changes involving HMGA2 in the stromal environment, preceding any mutations in neighboring epithelial cells via paracrine signaling." (PMID 39085703, 2024). "The BER-supporting function of HMGA2 enhances the ability of cancer cells to efficiently repair underlying lesions at the appropriate time." (PMID 39085703, 2024). "HMGA2 expression correlates with the level of malignancy directly, and is linked to enhanced metastatic potential and poor clinical outcomes in different cancers." (PMID 38778348, 2024). "Previous studies have implicated HMGA2 in the differentiation, transformation, proliferation, and metastasis of malignant cells of different cancers." (PMID 38361751, 2024). "For instance, a meta-analysis of 19 different malignancies suggested that the expression of HMGA2 presented upregulation in most cancer types, and HMGA2 overexpression was associated with vascular invasion, lymphatic metastasis, and poor prognosis." (PMID 38361751, 2024). "We also performed double IHC staining for HMGA2 and αSMA, a marker of cancer-associated fibroblasts." (PMID 38493165, 2024). "HMGA2 overexpression has been and is associated with poor prognosis, low survival rates, and advanced stage in various types of human cancer." (PMID 38845972, 2024). "Overexpression of HMGA2 is strongly associated with malignant transformation and tumor spread in various cancers." (PMID 39507236, 2024). "Due to its multifaceted role in cancer development and progression, HMGA2 has emerged as a potential diagnostic and prognostic cancer marker." (PMID 39085703, 2024). "In practice, 5-FU causes base lesions that promote replication fork stalling in proliferating cancer cells, and HMGA2 overexpression is associated with 5-FU chemoresistance in CRC patients." (PMID 36980621, 2023).
cancer (continued). "To date, some studies have investigated the HMGA2 gene, another member of the high-mobility group family, to identify molecular diagnostic and prognostic markers in cancer using minimally invasive processes." (PMID 35948739, 2022). "HMGA2 functions as a chromatin architectural factor and plays a relevant and causal role in cancer onset and development by virtually influencing all cancer hallmarks." (PMID 35213273, 2022). "Many studies aimed at addressing the functions of Hmga2 have been done in cancer cells, mostly because of its possible pathogenic role in various types of tumors." (PMID 35918713, 2022). "The HMGA2-KO MKN-45/MGC-803 cells together with their parental version were used to verify the anti-cancer efficacy of inhibiting HMGA2 and CDK13 associatively." (PMID 34513922, 2021). "RAS and HMGA2 are known to be translationally downregulated by the let-7 microRNA family, and loss of let-7 expression led to progression of some human cancers." (PMID 34302528, 2021). "HMGA2 has frequently been found in benign as well as malignant tumors and a significant association between HMGA2 overexpression and poor survival in different malignancies was described." (PMID 34302528, 2021). "Among them, LIN28A and HMGA2 have been implicated in cancer initiation, progression, and chemoresistance, and both serve as markers of CSCs." (PMID 34572843, 2021). "Broadening the search to genes previously associated with other cancer types in Cancercensus, we identified three other genes overlapping with CpG sites identified as candidate CpGDMs (HMGA2, GNA13, and STK33)." (PMID 33145876, 2021). "Studies have reported that the miR‐let‐7 family is associated with HMGA2, through which it co‐regulates many cancers." (PMID 32000296, 2020). "They found that high HMGA2 expression is associated with shorter overall and disease-free survivals in cancer patients." (PMID 31581665, 2019). "In conclusion, this meta-analysis confirmed that high HMGA2 expression in cancer is linked to poor prognosis, and HMGA2 is a potential predictive biomarker for OS." (PMID 29416690, 2018). "Pooled results also demonstrated that high HMGA2 expression was associated with shorter DFS in cancer patients (HR = 2.49, 95% CI = 1.44-4.28)." (PMID 29997523, 2018). "To assess the effect of Hmga2-deficiency on cancer cell dissemination and metastasis, we quantified the development of -metastases by fluorescence-stereomicroscopy." (PMID 30228296, 2018). "In order to gain further insight into the value of HMGA2, we investigated the association between HMGA2 level and certain clinicopathological parameters in cancers." (PMID 29997523, 2018). "Significant association between high expressed HMGA2 and poor overall survival in patients was found in 14 types of cancers." (PMID 29997523, 2018). "Numerous in vitro studies across several different human cancer types have suggested a role for HMGA2 in controlling phenotypes associated with malignant transformation and metastasis." (PMID 30228296, 2018). "The results indicated that high HMGA2 expression in human cancers was linked to aggressive biological behavior." (PMID 29997523, 2018). "As a result, the pooled data indicated that elevated HMGA2 was significantly associated with poor OS in patients with cancers (HR = 1.88, 95% CI = 1.68-2.11, P < 0.001)." (PMID 29997523, 2018). "HMGA2 is commonly overexpressed in numerous malignant cancers and is associated with increased invasiveness, stemness and a poor prognosis due to mediating downstream pathways, such as the TGFβ and Akt pathways." (PMID 29515783, 2018). "HMGA2 is highly expressed in embryonic tissues and many malignant tumors, and overexpression of HMGA2 is associated with EMT, metastasis and poor prognosis in several cancers." (PMID 28638102, 2017). "Although the expression and function of HMGA2 have been extensively studied in many cancers, the role of HMGA2 in human GC and its association with VM remain largely uncharacterized." (PMID 28533522, 2017).